VPS45 (vacuolar protein sorting 45 homolog)
Description:
May play a role in vesicle-mediated protein trafficking from the Golgi stack through the trans-Golgi network.
Synonyms: h-VPS45; VPS45A; VPS45B; H1; H1VPS45; SCN5; VPS54A; VSP45; VSP45A
Tractability: Antibody: UniProt places it where antibodies can reach, with medium confidence. PROTAC: ubiquitination databases record sites on it; its protein half-life has been measured.
Gene: Protein-coding gene on chromosome 1 (150,067,279 to 150,145,329, forward strand). Ensembl gene ENSG00000136631.
Subcellular location: Golgi apparatus membrane; Endosome membrane
Subcellular location (Human Protein Atlas): Microtubules
Pathways (Reactome):
Disease: SARS-CoV-2 modulates autophagy
Hemostasis: Factors involved in megakaryocyte development and platelet production
Vesicle-mediated transport: Intra-Golgi traffic
Gene Ontology:
Molecular function: protein binding
Biological process: intracellular protein transport; vesicle-mediated transport
Cellular component: endosome membrane; Golgi apparatus; Golgi membrane; membrane; cytoplasmic vesicle; endomembrane system; synaptic vesicle
Genetic constraint (gnomAD): Loss-of-function variants: 29 observed, 62.9 expected, observed/expected ratio (o/e) 0.46, 90% interval 0.34 to 0.63. The upper end of that interval is the gene's LOEUF score, 0.63, which puts it in group 2 of 6, group 1 being the genes least tolerant of losing a copy. Missense variants: 523 observed, 660.72 expected, observed/expected ratio (o/e) 0.79, 90% interval 0.74 to 0.85. Synonymous variants: 204 observed, 235.36 expected, observed/expected ratio (o/e) 0.87, 90% interval 0.77 to 0.97.
Homologues: Orthologues: chimpanzee VPS45 (99% identical), macaque VPS45 (99% identical), pig VPS45 (99% identical), dog VPS45 (99% identical), rat Vps45 (97% identical), mouse Vps45 (97% identical), guinea pig VPS45 (97% identical), tropical clawed frog vps45 (82% identical), zebrafish vps45 (82% identical), Drosophila melanogaster Vps45 (54% identical), Caenorhabditis elegans vps-45 (45% identical). Paralogues in human: STXBP2 (23% identical), STXBP3 (22% identical), SCFD1 (21% identical), VPS33A (17% identical), VPS33B (15% identical), SCFD2 (12% identical).
Diseases named in the same sentence as VPS45 in open-access papers:
VPS45 is named in the same sentence as 30 diseases in open-access papers, as found by Europe PMC text mining. Sharing a sentence is not in itself a finding about the gene and the disease. The quoted sentences say what the papers report.
congenital neutropenia (4 papers, 2014 to 2023). "The knowledge of VPS45-related disease in humans is limited to its association with congenital neutropenia." (PMID 34732130, 2021). "Indicating their importance in granulocyte development, another VPS protein, VPS45 was recently found to be mutated in severe congenital neutropenia patients." (PMID 25165726, 2014). "In accordance with other severe congenital neutropenias, VPS45 mutant patients had severe infections and their neutrophils and bone marrow myeloid cells showed accelerated apoptosis." (PMID 25165726, 2014).
neutropenia (4 papers, 2014 to 2024). A decrease in the number of neutrophils found in the blood. "Children with vacuolar protein sorting 45 homolog (VPS45) deficiency clinically present with neutropenia and myelofibrosis in the first year of life and progress to overt BM failure." (PMID 38374263, 2024). "Missense mutations leading to depletion of Vps45, a known Rbsn-5 binding partner, have recently been reported in patients with severe neutropenia, bone marrow fibrosis and early lethality." (PMID 25233840, 2014). "In addition, LOF mutations in human VPS45, encoding a regulator of endosomal membrane trafficking, have been associated with neutropenia, neutrophil dysfunction, nephromegaly and bone marrow fibrosis, with the reduced neutrophil count recapitulated in zebrafish vps45 KD embryos." (PMID 37047441, 2023).
bone marrow fibrosis (2 papers, 2014 to 2023). "In 2013, a homozygous missense variant in VPS45 gene, which encodes a protein essential for membrane trafficking, was first reported as a cause of a novel syndromic form of SCN (SCN5), characterized by progressive bone marrow fibrosis, organomegaly, and osteosclerosis." (PMID 38089934, 2023).
cataract (1 paper, 2018). Partial or complete opacity of the crystalline lens of one or both eyes that decreases visual acuity and eventually results in blindness. "Further studies on the downstream pathway in vps45 mutants will advance understanding of spatial regulation of lens fiber differentiation and provide insight into the pathological process of secondary cataracts." (PMID 30322969, 2018).
cryptococcosis (1 paper, 2018). An acute or chronic, localized or disseminated infection by Cryptococcus neoformans. "Given the contributions of Vps45 to capsule formation and the influence of host temperature on mutant phenotypes, we next tested the importance of VPS45 for the development of cryptococcosis." (PMID 30071112, 2018). "The vps45 mutant was also attenuated for virulence in a mouse model of cryptococcosis and for survival in a macrophage-like cell line." (PMID 30071112, 2018).
deafness (1 paper, 2023). An inherited or acquired condition characterized by the complete loss of the ability to hear from one or both ears. "Defects in the 30 shared genes are related to several pathologies, such as vision abnormalities (TMEM135), cancer (CDH6, FZD10, TIAM2), neuropsychiatric disorders (Tenm4, Pde4dip, Grid2), deafness (TFB1M), neutrophil disorders (VPS45) and others." (PMID 36902345, 2023).
myelofibrosis (1 paper, 2024). A partial or complete replacement of the bone marrow stroma by fibrous tissue. "In contrast to controls, VPS45-mutant BMOs showed increased deposition of reticulin fibers, reminiscent of myelofibrosis in BM biopsies of VPS45-deficient patients." (PMID 38374263, 2024).
non-small cell lung carcinoma (1 paper, 2022). A group of at least three distinct histological types of lung cancer, including non-small cell squamous cell carcinoma, adenocarcinoma, and large cell carcinoma. "In non-small cell lung cancer, SPI1 exerted an oncogenic role via upregulation of lncRNA SNHG6 and miR-485-3p/VPS45 axis." (PMID 35945192, 2022).
nonsmall-cell lung cancer (1 paper, 2023). "SPI1-induced upregulation of lncRNA SNHG6 promotes nonsmall-cell lung cancer via miR-485-3p/VPS45 axis." (PMID 36967718, 2023).
ovarian carcinoma (1 paper, 2019). A malignant neoplasm originating from the surface ovarian epithelium. "In this study, we identified six novel genes, MSL3, ZNF691, VPS45, ITGB3BP, TLE2, and ZNF498 whose expression altered the proportion of the SP cells of ovarian cancer cells through a functional genomics screen." (PMID 31578411, 2019). "In summary, using a functional genomics screen, we identified six novel genes, MSL3, ZNF691, VPS45, ITGB3BP, TLE2, and ZNF498, that regulate the proportion of SP cells in ovarian cancer." (PMID 31578411, 2019). "In conclusion, through a functional genomics screen using an shRNA library we identified six novel genes; MSL3, ZNF691, VPS45, ITGB3BP, TLE2 and ZNF498, whose downregulation individually increased the proportion of SP cells and the malignant phenotypes of ovarian cancer." (PMID 31578411, 2019). "In ovarian cancer cases, low expression of MSL3, ZNF691 and VPS45 was related to poor prognosis." (PMID 31578411, 2019).
Schwachman Diamond Syndrome (1 paper, 2019). "On the contrary, more data is available on Schwachman Diamond Syndrome and deficiency of VPS45 protein, and is presented here." (PMID 31709206, 2019).
viral infection (1 paper, 2015). "Among them, 22 genes (Gm26130, mt-Ts2, Mgst2, Cyp7a1, Vps45, etc.)were clustered as a hot block next to a block containing Irf7 gene that is the master regulator for the induction of type I interferon during viral infection." (PMID 25902143, 2015).
infection (3 papers, 2014 to 2022). The state of being infected such as from the introduction of a foreign agent such as serum, vaccine, antigenic substance or organism. "Parasites lacking Vps45 quickly incorporated host GFP 7 minutes after infection and showed an increased intracellular GFP staining compared to wild-type parasites." (PMID 33082261, 2020).
cancer (2 papers, 2018 to 2023). A tumor composed of atypical neoplastic, often pleomorphic cells that invade other tissues. "In addition, this correlation analysis revealed cancer-specific addiction associated with coordinated upregulation of another subset of genes that reside in the same region of chromosome 1 and are involved in vesicle and protein trafficking (GBA, GPR89A, NCSTN, PSMD4, VPS45)." (PMID 29535384, 2018).
tumor (2 papers, 2016 to 2019). "The average expression levels of VPS45, WIPI1, TTC1, IGBP1 and KLHL21 genes in all tested HCC tissues were greatly increased compared with those in the adjacent non-tumor tissues, showing the similar results to microarray data." (PMID 27769251, 2016).
VPS45 also shares sentences with these, for which no sentence is quoted: schizophrenia (2 papers); 3-methylglutaconic aciduria (1); arthrogryposis (1); Barth syndrome (1); Cirrhosis (1); Cohen syndrome (1); COVID-19 (1); cyst (1); Glucose intolerance (1); glycogen storage disease type 1b (1); nematode infections (1); nephromegaly (1); Obesity (1); osteosclerosis (1); Thyroid adenoma (1).